INS (insulin)
Diseases named in the same sentence as INS in open-access papers (continued):
Sharing a sentence is not in itself a finding about the gene and the disease.
diabetes (continued). "Insulin secretory dysfunction and insulin resistance can lead to diabetes mellitus (DM), a disease that accounts for increased cardiovascular morbidity, mortality, and healthcare costs." (PMID 35454166, 2022). "Type 2 diabetes mellitus (T2DM) is a chronic metabolic disorder characterized by elevated levels of blood glucose due to insulin resistance or insulin-secretion defects." (PMID 36547924, 2022). "A strong case can be made for PGC-1α4 as a potential target for therapeutic research to improve insulin sensitivity, and prevent diabetes and cardiometabolic diseases." (PMID 35484130, 2022). "External insulin is the only option for treating patients with type I and II diabetes, showing the importance of insulin and its analogs." (PMID 35723344, 2022). "The basis of the metabolic abnormalities in carbohydrate, fat, and protein in diabetes is insufficient action of insulin in various target tissues." (PMID 35711333, 2022). "Thirteen patients (n=1, 5, 0, 7 for MHO, HMO-U, HMO-I, and LMO, respectively) used anti-diabetes medication because of inadequate glucose control or insulin resistance." (PMID 36407309, 2022). "Lipohypertrophy (LH) is a common complication of insulin therapy in subcutaneous tissue observed in patients with diabetes." (PMID 35111222, 2022). "Clinically, diabetes has been classified as either emanating from autoimmunity against the insulin-producing β cell (type 1 diabetes, T1D) or from an inability of the β cell to compensate for peripheral tissue insulin resistance (type 2 diabetes, T2D)." (PMID 35817393, 2022). "The HFD-fed animals in our study developed signs of type 2 diabetes mellitus, such as elevated fasting glucose and insulin levels." (PMID 36555360, 2022). "Oxytocin prevents marked deterioration in pancreatic ß-cell function with subsequent marked improvement in insulin secretion in comparison to untreated diabetes." (PMID 35462799, 2022). "Ketoacidosis was determined to be induced by acute hyperglycemia secondary to pancreatitis, which suppresses insulin secretion transiently." (PMID 35664400, 2022). "Diabetes mellitus (DM) is a chronic carbohydrate metabolism disease characterized by hyperglycemia, and it is caused by a total lack of insulin, insufficient secretion or synthesis of insulin or peripheral resistance to the insulin effect." (PMID 36559668, 2022). "LC-MS/MS based methods can even differentiate between the isobaric LisPro (Humalog) insulin used to treat diabetes and endogenous insulin, due to a signature product ion derived from the transposition of the proline and lysine residue." (PMID 36242807, 2022). "It affects carbohydrate metabolism, β-cell function, insulin sensitivity, and IR in the treatment of diabetes mellitus and its complications." (PMID 35431942, 2022). "A history of diabetes mellitus was found in nine (24%) patients (all type 2 diabetes mellitus), of whom two (5%) patients were administered insulin and two (5%) patients were receiving oral hypoglycemic drugs." (PMID 35457586, 2022). "Diabetes mellitus is a group of metabolic diseases characterized by chronic hyperglycaemia resulting from defects in insulin secretion, insulin action, or both." (PMID 35855025, 2022). "Diabetes is a chronic illness characterized by elevated blood glucose levels due to cellular resistance to insulin, insufficient insulin production by pancreatic β-cells, or both." (PMID 36558920, 2022). "Among potential tools to improve glycemic control, the use of diabetes technologies – insulin pumps and Continuous Glucose Monitoring (CGM) — were identified." (PMID 36992759, 2022). "Ideally, the analysis should be conducted in a prospective cohort spanning from NGT to diabetes to insulin requirement although this would require a large sample size with long follow‐up period and enough events for both outcomes." (PMID 35174618, 2022).
diabetes (continued). "GO function and KEGG pathway analysis suggested that DERNAs were significantly enriched in diabetes-related regulatory processes, including regulation of insulin secretion, carbohydrate metabolism, response to glucose, vitamin metabolism, and lipid metabolism." (PMID 36360309, 2022). "HbA1c and total daily insulin were evaluated at 3 (T1), 6 (T2) and 12 (T3) months post-baseline (T0, diabetes onset), QoL after 1 year." (PMID 35784525, 2022). "Lipodystrophy is the most common dermatological complication in patients with diabetes on insulin therapy." (PMID 35884071, 2022). "Diabetes-related parameters, including fasting blood glucose, HbA1c, c-peptide, and insulin level, also showed a significant decline (p < 0.05)." (PMID 35277004, 2022). "While insulin desensitization in diabetes is driven by high glucose and insulin levels, insulin desensitization in the brain of AD patients is most likely driven by chronic inflammation." (PMID 36012569, 2022). "Pancreatic insulin expression of these mice was comparable to wild‐type mice, and islets appeared much healthier than vehicle‐treated mice which had severe diabetes." (PMID 36257905, 2022). "Our patient, an 11-year-old male from Saudi Arabia with G6PD deficiency and insulin-dependent diabetes mellitus (IDDM), has been on multiple daily injection (MDI) insulin therapy." (PMID 35444908, 2022). "With this information, we can characterize C3 as diabetics who take mainly biguanides and cluster C5 as diabetics insulin-dependant." (PMID 36064616, 2022). "In the present study, we evaluated the potential of an alum-formulated, insulin peptide vaccine to prevent T1D in the NOD mouse model when administered during late-stage pre-diabetes." (PMID 36339431, 2022). "The lack of correlation in our study is likely due to potential confounders of insulin therapy modality and diabetes management, excluding individuals with T1D who had diabetic complications and a small sample size." (PMID 36142941, 2022). "Many studies have been conducted to make insulin-producing cells from stem cells or other cells and use them as a cell therapy for diabetes treatment." (PMID 35214135, 2022). "Oral hypoglycemic drugs and insulin are currently the main effective drugs in the treatment of diabetes, but chronic consumption of these drugs has certain side effects." (PMID 35211009, 2022). "In diabetes, insulin secretion is enhanced by β-endorphin via activation of μ-receptors in the pancreas." (PMID 35822185, 2022). "Firstly, the mechanisms of obesity-induced diabetes include adipocytes increase, insulin resistance, inflammatory cytokines and relevant adipokines secretion." (PMID 36183132, 2022). "C3G from black soybeans showed anti-diabetes effects by inducing the differentiation of 3T3-L1 preadipocytes into smaller and insulin-sensitive adipocytes." (PMID 35630767, 2022). "Cellular oxidative stress is also proposed to affect insulin sensitivity by inducing insulin signal disruption and adipocytokine dysregulation, thus contributing to diabetes development." (PMID 36295825, 2022). "Diabetes stigma was frequently cited as a barrier to insulin among diabetes patients in different communities." (PMID 36554673, 2022). "We found that patients with SIDD and SAID were treated in a similar manner throughout the diabetes period, with a significant need for insulin therapy, as demonstrated in previous studies." (PMID 36457559, 2022). "Blood glucose, insulin, C-peptide, and glycated hemoglobin (HbA1c) are commonly used monitoring indicators for the diagnosis and management of diabetes." (PMID 36291040, 2022). "Type 2 diabetes mellitus (T2DM) is a condition characterized by insufficient insulin production or insulin resistance." (PMID 36249459, 2022). "The Diabetes:M, mySugr, and OneTouch Reveal® apps include insulin bolus calculators to modify insulin doses according to individual needs." (PMID 36612402, 2022).
diabetes (continued). "Chronic hyperglycemia, hyperlipidemia, and hyperacidemia with reduced insulin secretion or action (or both) characterize diabetes mellitus (DM)." (PMID 35774744, 2022). "That change in metabolism is part of the process of glucose-stimulated insulin secretion and is of particular interest in the context of diabetes." (PMID 36251711, 2022). "In stable patients with diabetes receiving continuous PN, the subcutaneous injection of a long-acting insulin is useful." (PMID 36992742, 2022). "Diabetes mellitus is a chronic metabolic disorder identified by inadequate insulin secretion, or resistance to insulin action, or both." (PMID 37693084, 2022). "Db/db mice are obese, highly insulin - and leptin-resistant and spontaneously and progressively develop worsening diabetes over time culminating in beta cell mass depletion." (PMID 36992750, 2022). "A previous study showed that the insulin sensitizing agent pioglitazone significantly reduced the incidence of recurrent CVD in patients with diabetes mellitus, partly mediated by increased IR." (PMID 36482415, 2022). "Rouse and Finlay (2016) found that responsibility for insulin was constructed as shared – staff worked together with the person with diabetes to make decisions and facilitate insulin administration." (PMID 35983585, 2022). "The patient with diabetes mellitus had better blood sugar control with a lower-than-usual requirement for basal insulin." (PMID 36381721, 2022). "Insulin secretion was thought to be reduced in the OLETF rats in the O-C group by the progression of diabetes in accordance with the results of a previous study." (PMID 35100325, 2022). "Diabetes numeracy skills are required in the interpretation of food labels, insulin pump dosage, the interpretation of blood glucose meter data, and the determination of carbohydrate intake." (PMID 36078271, 2022). "Type 2 diabetes mellitus is a metabolic disease characterized by insulin resistance or defective insulin secretion by pancreatic β-cells." (PMID 36618710, 2022). "Of all patients with diabetes, 123/124 used bolus insulin and almost all −121/124 used also a basal type of insulin." (PMID 35873426, 2022). "Diabetes mellitus, a group of metabolic disorders with abnormalities of insulin secretion, insulin action, or both resulting from various etiologies is defined by elevated serum glucose levels or persistent hyperglycemia." (PMID 35761309, 2022). "In human studies, it has usually been reported that there is a strong association between dietary BCAAs and /or blood levels of BCAAs with impaired insulin and glucose metabolism, metabolic syndrome and diabetes." (PMID 35031039, 2022). "This disease can be classified as Type 1 Diabetes (T1D), when the body produces an inadequate amount of insulin, and Type 2 Diabetes (T2D), when the body cannot use insulin efficiently, being the predominant diabetes type." (PMID 36613315, 2022). "The inhibition of IKKε limited the inflammatory response in vivo and improved insulin sensitivity and glucose/lipid metabolism in patients with obesity and diabetes, which proposed a potential therapeutic approach." (PMID 35662709, 2022). "Most technological advances developed as tools for better T1D self-care are mainly design artifacts, such as portable blood glucose meters, insulin pens and pumps, enabling improvements in diabetes management." (PMID 36420398, 2022). "A gradual decline in insulin secretion from normal glucose tolerance to impaired glucose tolerance to type 2 diabetes mellitus in adolescents with obesity has been documented." (PMID 35268007, 2022). "Impaired memory ability and reduced hippocampal synaptic plasticity were shown to be restored by insulin treatment in an experimental model of diabetes mellitus." (PMID 35615716, 2022). "Studies analysing data by quartiles report independent associations between sedentary behaviour and fasting insulin, HOMA-IR and diabetes only for high duration of sedentary time (7–9 hours/day)." (PMID 35544519, 2022).
diabetes (continued). "Glucose toxicity can curtail insulin synthesis in β-cells and contributes to cell dysfunction, which is involved in the pathogenesis of diabetes mellitus." (PMID 35841066, 2022). "A project to improve the community nursing team's insulin administration service for vulnerable homebound adults with diabetes." (PMID 35983585, 2022). "Previous studies have established that the KATP channel plays an essential role in insulin secretion and is a drug target for diabetes." (PMID 35847046, 2022). "Diabetes mellitus is a lifelong, incurable disease in which the production or response to insulin is dysregulated." (PMID 35324794, 2022). "There are also reports of other mental illnesses that coexist with diabetes, which often lead to suicides using an excessive amount of insulin." (PMID 35324747, 2022). "Diabetes is a metabolic disorder in which changes in plasma levels of glucose occur as a result of defects in insulin secretion or insulin action." (PMID 36293500, 2022). "The disease of type 2 diabetes mellitus (T2DM) is principally induced by insufficient insulin secretion and insulin resistance." (PMID 36337615, 2022). "Efforts to produce insulin-secreting replacement cells to treat diabetes require reliable tools to assess islet cellular identity." (PMID 35440614, 2022). "Continuous administration of natural GLP-1 increases insulin levels and results in lower blood glucose and hemoglobin A1C (HbA1c) levels in patients with type 2 diabetes mellitus (T2DM)." (PMID 36465634, 2022). "This understanding paves the way for the development of improved insulin therapies for people living with diabetes." (PMID 35671972, 2022). "In summary, we provide evidence that the upregulation of UCP2 in stressed β-cells under diabetes decreased insulin secretion due to mitochondrial dysfunction and impairment of Ca2+ release from the ER by inducing AldB expression." (PMID 35800776, 2022). "Diabetes accounts for altered insulin secretion and resistance, along with the decreased sensitivity of target organs towards insulin, which is eventually followed by fat, protein, water, electrolytes, and other metabolic disorders." (PMID 36615695, 2022). "Nicotine affects cardiac contractility and heart rate, increases blood pressure, reduces sensitivity to insulin, aggravates diabetes, and results in endothelial dysfunction." (PMID 36111119, 2022). "For the 2,412 patients with current diabetes, 48 subjects were identified to have type 1 diabetes (currently using insulin and diagnosed with diabetes under age 30)." (PMID 35237556, 2022). "First, long‐term diabetic patients featured by insufficient insulin secretion weakens endothelial cell function and inhibits the generation of nitric oxide (NO) in comparison to short‐term diabetes patients mainly characterized by insulin resistance." (PMID 35941828, 2022). "Since no drug has a better overall glycemic response, a majority of patients eventually need additional oral drugs and insulin to maintain glucose homeostasis while reducing diabetes-related complications." (PMID 36532503, 2022). "The RRRs for GC induced diabetes and preexisting diabetes were significantly higher with all three insulin treatments." (PMID 34986826, 2022). "The impact of insulin was almost miraculous as those destined to die from their diabetes mellitus returned to life." (PMID 35152907, 2022). "The exclusion of patients with diabetes using exogenous insulin or with micro- or macrovascular complications makes the results of this study limited to the characteristics of this sample and should be extrapolated with caution." (PMID 36145115, 2022). "In a study investigating the association between obesity and insulin concentration, we noted that abdominal fat distribution is closely related to insulin concentration; thus, waist circumference is considered a useful indicator of diabetes induction." (PMID 36193302, 2022).
diabetes (continued). "In our recent descriptive study characterizing diabetes in rural Rwanda, we found that more than half the people with diabetes were classified as type 1 diabetes based on clinical features, including early insulin treatment requirement." (PMID 35465373, 2022). "In patients with COVID-19, a patient can develop diabetes mellitus or worsening hyperglycemia in already known diabetic patients due to damage to the b cells and reduced insulin secretion endogenously." (PMID 36721573, 2022). "Type 1 Diabetes Mellitus (DM1), diabetes is a chronic degenerative metabolic illness, due to the destruction of the insulin-producing beta cells." (PMID 35204864, 2022). "In diabetes, however, skeletal muscle cells are resistant to insulin signaling, and glucose entry into the cytoplasm is impaired." (PMID 35323702, 2022). "Diabetes mellitus (DM) is a serious lifelong autoimmune disease characterized by hyperglycemia and low insulin level in the blood." (PMID 36535972, 2022). "Diabetes is a chronic, metabolic hyperglycemic disorder and occurs due to impaired secretion or function of insulin, or both." (PMID 35029893, 2022). "Insulin pens, syringes, pumps, sugar testing devices, strips, diabetes medical alert bracelets, etc. are the devices necessary for individuals with diabetes." (PMID 36699937, 2022). "Type 2 diabetes mellitus (T2DM) is a chronic metabolic syndrome associated with hyperglycemia, impaired insulin sensitivity, low-grade inflammation, beta-cell failure, and impaired metabolism of glucose, proteins, and lipids." (PMID 36276816, 2022). "Short-term intensive insulin therapy is very important in type 2 diabetes mellitus, which was given by either continuous subcutaneous insulin infusion or multiple daily injections for 14–21 days." (PMID 35459162, 2022). "Alternatively, use of the single question ‘I take less insulin than I should’ has been identified as potentially important for detecting eating disorder symptomology in people with diabetes who are using insulin." (PMID 35978344, 2022). "More than 95% of people with diabetes have type 2 diabetes (T2D), a disease that results from the body’s ineffective use of insulin and is largely the result of excess body weight and physical inactivity." (PMID 35630761, 2022). "R-glucosidase inhibitors can cure diabetes mellitus by suppressing intestinal R-glucosidases, which lower diet-induced hyperglycemic activity and internal insulin production." (PMID 36144587, 2022). "This hormone secreted by adipose tissue resists the action of insulin and impairs glucose homeostasis, leading to the development of type 2 diabetes mellitus (DM2)." (PMID 36289594, 2022). "Herein, we aimed to evaluate the therapeutic effect of P. edulis fruit peel aqueous (AFA) extract adjuvant to insulin as a potential nephroprotective agent against streptozotocin-induced diabetes." (PMID 36266308, 2022). "Hyperglycemia activates the pancreatic RAS, resulting in reduced insulin release and increased β-cell death in diabetes." (PMID 36248064, 2022). "Diabetes mellitus is a complex and multi-factorial metabolic syndrome characterized by insulin secretion or insulin activity defects, resulting in hyperglycemia." (PMID 35787282, 2022). "As a treatment option for people living with diabetes, automated insulin delivery (AID) systems are becoming increasingly popular." (PMID 36992765, 2022). "This can be attributed to the duration of diabetes, pronounced beta cell destruction, nutritional mal-absorption, improper insulin dosage and administration by the patients." (PMID 35819935, 2022). "This study shows that older adults with T1D were able to continue to use diabetes-related technologies, such as insulin pump and CGM, during a time of isolation, to maintain their diabetes management." (PMID 36256804, 2022). "Diabetes mellitus (DM) is a group of metabolic diseases characterized by chronic hyperglycemia as a result of defects in insulin secretion and/or function." (PMID 36297643, 2022).